LAT2 (linker for activation of T cells family member 2)
Diseases named in the same sentence as LAT2 in open-access papers (continued):
Sharing a sentence is not in itself a finding about the gene and the disease.
osteosarcoma (5 papers, 2022 to 2025). A usually aggressive malignant bone-forming mesenchymal neoplasm, predominantly affecting adolescents and young adults. "LAT2 expression in tumor-associated macrophages was much lower than tumor cells in osteosarcoma tissues." (PMID 36274066, 2022). "Here the authors show that doxorubicin promotes IL-18 secretion by tumor associated macrophages inducing LAT2-dependent CD47 upregulation in osteosarcoma cells, suggesting LAT2 inhibition as a therapeutic option in combination with doxorubicin." (PMID 36274066, 2022). "The association of a locus in the SLC7A8 gene to EDP may be caused by an interaction of LAT2 with chemotherapeutics that are used in the treatment of osteosarcoma." (PMID 36438828, 2022). "Increased uptake of leucine and glutamine in osteosarcoma cells through upregulation of LAT2 activates mTORC1 and subsequent c-Myc-mediated transcription of CD47, enabling evasion of innate immune mechanisms and thereby promoting metastasis." (PMID 37197432, 2023). "To determine the role of LAT2-mediated amino acid uptake in doxorubicin-induced osteosarcoma immune evasion, we subcutaneously injected LAT2-depleted HOS cells into nude mice and treated the tumor-bearing mice with doxorubicin." (PMID 36274066, 2022). "At our current state of knowledge, little is known on the role and function of LAT2 in osteosarcoma or osteosarcoma treatment response, although it has been assessed in pharmacogenetic studies in other cancer types." (PMID 36438828, 2022). "Chemotherapy activates tumor-associated macrophages to secrete IL-18, which in turn induces LAT2 expression and LAT2-mediated Gln and Leu uptake in osteosarcoma cells." (PMID 36274066, 2022). "IHC analysis of paired pre- and post-chemotherapy specimens from osteosarcoma patients revealed chemotherapy significantly increased LAT2 expression." (PMID 36274066, 2022). "Inhibition of LAT2-mediated CD47 upregulation in osteosarcoma cells augments macrophage phagocytosis and sensitized tumor cells to chemotherapy." (PMID 36274066, 2022). "Altogether, doxorubicin, and not methotrexate or cisplatin, was shown to be a substrate for LAT2 which gives novel implications for the role of LAT2 in osteosarcoma therapy response to doxorubicin." (PMID 36438828, 2022). "In addition, the expression of LAT2 was positively correlated with expression of IL-18 as well as the expression of CD47 in osteosarcoma specimens before and after chemotherapy." (PMID 36274066, 2022). "We hypothesize that increased LAT2 expression in osteosarcoma tissue could lead to increased uptake of doxorubicin, therefore higher intracellular exposure and improved cell death." (PMID 36438828, 2022). "Functional studies indicate LAT2-mediates uptake of doxorubicin, which could give new opportunities to personalize treatment of osteosarcoma patients." (PMID 36438828, 2022). "Our results may have novel implications for personalized treatment of patients with osteosarcoma, because we suggest that LAT2-mediated doxorubicin uptake in osteosarcoma tumor cells could play an important role in treatment resistance and eventually treatment response." (PMID 36438828, 2022). "Depletion of LAT2 or treatment of tumor cells with a LAT inhibitor downregulates CD47 with enhanced macrophage infiltration and phagocytosis of tumor cells, and sensitizes osteosarcoma to doxorubicin treatment in mice." (PMID 36274066, 2022). "In combination with the association of LAT2 expression in tumor tissue with improved survival in patients without metastasis, LAT2-mediated doxorubicin transport could mechanistically explain the association of genetic variation in SLC7A8 that is associated with EDP in patients with osteosarcoma." (PMID 36438828, 2022). "However, our non-significant results are in contrast with those expected if LAT2 led to mTORC1 phosphorylation suggesting no LAT2-mediated mTOR phosphorylation in tissue of osteosarcoma patients." (PMID 36438828, 2022).
osteosarcoma (continued). "However, a potential interaction between LAT2 and osteosarcoma chemotherapeutics has never been investigated." (PMID 36438828, 2022). "Our results show that patients with expression of LAT2 in osteosarcoma tissue may have better survival compared to patients without expression of LAT2, especially in patients that present without metastases." (PMID 36438828, 2022). "Finally, SLC7A8 mRNA expression analysis and LAT2 immunohistochemistry of osteosarcoma tissue showed that the lack of LAT2 expression is a prognostic factor of poor prognosis and reduced overall survival in patients without metastases (p = 0.0099 and p = 0.14, resp)." (PMID 36438828, 2022).
age-related hearing loss (3 papers, 2019 to 2025). "Functional studies of human SLC7A8 variants (14:23597290A/T, 14:23598917G/A, 14:23608641C/T, 14:23598870G/A) found in age-related hearing loss (ARHL) patients showed decreased LAT2 transport activity, further supporting the causative link." (PMID 41142409, 2025). "Whereas the loss of LAT2-dependent transport function is attributed to age-related hearing loss, renal aminoaciduria, and cataract formation, an elevated expression level of LAT2 is linked to cancer." (PMID 32993041, 2020). "Thus, LAT2 deficiency compromises the supply of key neutral amino acids essential for maintaining cochlear cell integrity and auditory processing, contributing directly to the development of age-related hearing loss." (PMID 41142409, 2025). "LAT2 deficiency, caused by mutations or deletion of the SLC7A8 gene encoding the L-type amino acid transporter 2, has also been linked to age-related hearing loss (ARHL) through its critical role in amino acid transport in the inner ear." (PMID 41142409, 2025).
breast carcinoma (3 papers, 2012 to 2022). "When looking at expression of LAT2 in tumor tissues, LAT2 expression was associated with improved survival in estrogen receptor positive (ER+) breast cancer and in lung cancer." (PMID 36438828, 2022). "Human breast cancer cells, including MCF-7, were shown to express LAT1 (SLC7A5) and LAT2 (SLC7A8); however, only SLC6A14 requires chloride ions for its activity." (PMID 34359969, 2021). "FOXP3 was shown to be involved in the induction of several tumor suppressors, including p21, p18, LAT2, and ARHGAPS in breast cancer." (PMID 23888189, 2012).
cholangiocarcinoma (3 papers, 2024 to 2025). A carcinoma that arises from the intrahepatic biliary tree (intrahepatic cholangiocarcinoma) or from the junction, or adjacent to the junction, of the right and left hepatic ducts (hilar cholangiocarcinoma). "In cholangiocarcinoma cells and animal models, curcumin suppresses the expression of SLC7A8 (LAT2) and works synergistically with gemcitabine to inhibit GLS and GS expression." (PMID 41515171, 2025). "In gemcitabine-resistant cholangiocarcinoma (CCA) cells, curcumin synergistically downregulates the expression of glutaminase (GLS) and glutamine synthetase (GS) by inhibiting LAT2-mediated glutamine (Gln) uptake in conjunction with gemcitabine." (PMID 41515171, 2025).
melanoma (3 papers, 2019 to 2025). A malignant, usually aggressive tumor composed of atypical, neoplastic melanocytes. "The three-gene KRAS-Macrophage Prognostic Associated Gene (KMPAG) signature, encompassing CLEC4A, CXCL10, and LAT2, emerges as a robust prognostic tool that correlates with distinct clinical and immunological phenotypes in melanoma cohorts." (PMID 40607411, 2025). "The macrophage-centric gene signature described in this study, comprising CLEC4A, CXCL10, and LAT2, furnishes robust evidence that macrophages can vary widely in their functional states within melanoma lesions." (PMID 40607411, 2025). "Moreover, CLEC4A expression exhibited significant correlations with CXCL10 (r = 0.706) and LAT2 (r = 0.851), suggesting potential cooperative roles of these genes in melanoma." (PMID 40607411, 2025). "The LAT1 in a primary melanoma is predominantly expressed over LAT2, ASCT2, and GLUT1." (PMID 31717859, 2019). "Carrier-mediated proteins overexpressed in melanoma cells include L-type amino acid transporter 1 (LAT1/SLC7A5), L-type amino acid transporter 2 (LAT2/SLC7A8), alanine-serine-cysteine transporter 2 (ASCT2/SLC1A5), and glucose uptake transporter 1 (GLUT1)." (PMID 31717859, 2019).
neuroendocrine tumors (3 papers, 2016 to 2022). "A previous study in neuroendocrine tumors showed that LAT1 and LAT2 expression in tumor cells caused increased l-DOPA uptake." (PMID 36438828, 2022).
brain tumor (2 papers, 2020 to 2024). "18F-FET is an amino acid that is transported into the brain and into brain tumour tissue by facilitated transport via large neutral amino acid transporters (subtypes LAT1 and LAT2)." (PMID 37848641, 2024). "This phenomenon has not only been reported for [18F]FET, but also for 11C-methonine, the longest established amino acid tracer for brain tumor imaging, which is taken up via the same amino acid transporter system LAT1/LAT2 as [18F]FET." (PMID 32409931, 2020).
diabetes (2 papers, 2020 to 2021). "Consistent with Western blot data, pregestational diabetes caused reduction of LAT1 and LAT2 expression in the placentas." (PMID 32156054, 2020). "Differentially regulated genes not overlapping with ERCB data also reflected diabetes-associated changes, such as extracellular matrix (ANGPTL4, TNN, DPT, COL9A2) or gestational diabetes (LAT2, HP, CXCL10, CD86, CD68, REN, SLC2A3, VCAM1)." (PMID 33923831, 2021).
glomerulonephritis (2 papers, 2014 to 2022). A renal disorder characterized by damage in the glomeruli. "A regulation of LAT2/4F2hc expression by mTORC1 has been described in glomerular epithelial cells: in glomerulonephritis conditions, mTORC1 integrates signals from inflammatory cytokines stimulating LAT2 translocation to plasma membrane." (PMID 25157349, 2014).
Hypertension (2 papers, 2021 to 2024). The presence of chronic increased pressure in the systemic arterial system. "A similar result was found for the marker of SLC7A8/LAT2 rs3783436-T/C, whose minor allele C resulted associated with reduced risk of hypertension when the G3 group was compared to the G4 in an additive model [OR = 0.56 (95% CI 0.35–0.90; p = 0.017]." (PMID 38890684, 2024). "It is difficult, however, to establish a clear correlation between dopamine levels, LAT2/4F2hc expression, and the risk of hypertension in the context of CKD, even in view of the pleiotropic effects that dopamine and the SLC7A8/SLC3A2 genes exert." (PMID 38890684, 2024). "Since L-DOPA is known to be converted to dopamine in proximal tubule cells and raise blood pressure, this report indicates the possibility that LAT2 can be the important factor that is related to the onset of hypertension." (PMID 33789576, 2021). "LAT2 has been also reported to be expressed at higher levels in renal cortex of spontaneously hypertensive (SHR) than in normotensive rats; its overexpression was associated with enhanced L-DOPA uptake and preceded the onset of hypertension." (PMID 38890684, 2024). "Considering that LAT2 also transports L-DOPA, which is known to be related to hypertension and some neurodegenerative diseases, the results of such studies may also contribute to the establishment of new targets for pathological treatment." (PMID 33789576, 2021).
lung carcinoma (2 papers, 2022 to 2024). "MiR-762, MST1, LAT2, YAP mRNA and protein, TWIST1, SMAD3 may be effective diagnostic biomarkers in both lung cancer patients and chronic inflammatory patients." (PMID 38589525, 2024).
allergic asthma (1 paper, 2025). A asthma with a basis in a pathological type I hypersensitivity reaction. "We noted that SLC7A5 (LAT1), SLC7A8 (LAT2), and SLC3A2 (CD98), part of LAT1 and LAT2 heterodimer complexes, were significantly downregulated in allergic asthma but not in allergic rhinitis, suggesting decreased transport of Phe into the Th2 cells in more advanced allergic disease." (PMID 41308641, 2025).
Aminoaciduria (1 paper, 2025). An increased concentration of an amino acid in the urine. "Mutations or dysfunctions in the SLC7A8 gene encoding LAT2 can impair the transporter's function, leading to aminoacidurias characterized by the abnormal excretion of amino acids in urine." (PMID 41142409, 2025). "The review highlighted 9 genes associated with aminoacidurias, including SLC3A1 (rBAT), SLC7A9 (bo,+AT), SLC6A19 (BoAT1), SLC7A7 (y+LAT1), SLC7A6 (y+LAT2), SLC36A2 (PAT-2), SLC6A20 (SIT-1), SLC6A18 (BoAT3), and SLC1A1 (EAAT3)." (PMID 41142409, 2025).
bile duct adenocarcinoma (1 paper, 2014). "Kaplan–Meier analysis showed a significant difference in prognosis between patients with bile duct adenocarcinomas having LAT1-high and -low scores, whereas LAT2 and CD98 expression and Ki-67 LI were not predictive of poor prognosis." (PMID 24890221, 2014).
Cachexia (1 paper, 2025). Severe weight loss, wasting of muscle, loss of appetite, and general debility related to a chronic disease. "To characterise the impact on muscle degradation, we tested LAT2 KO mice in cancer‐associated cachexia, streptozocin‐induced Type‐1 diabetes, and ageing models." (PMID 40546137, 2025).
clear cell renal cell carcinoma (1 paper, 2013). "To clarify the role of LATs in human clear cell renal cell carcinoma (RCC), we investigated the expression of mRNAs for LAT1, LAT2, LAT3, LAT4, and 4F2hc in clear cell RCC tissues." (PMID 24168110, 2013).
coccidiosis (1 paper, 2021). A parasitic infection caused by Coccidia. "The gene expression of GLUT2 and LAT2 was downregulated, but CAT1, GLUT1, and LAT1 were upregulated by coccidiosis." (PMID 34108017, 2021). "The mechanism of action by which coccidiosis increased GLUT1, LAT1, and CAT1, but decreased GLUT2 and LAT2 remains, however, unknown." (PMID 34108017, 2021).
colon cancer (1 paper, 2020). "In colon cancer cell lines, those with low expression of LAT2 are typically sensitive to LAT1 knock-out (e.g., RKO, HCC-78), while cell lines with higher levels of LAT2 are typically resistant (HT55, SW620)." (PMID 32859034, 2020).
crescentic glomerulonephritis (1 paper, 2021). A histopathologic term for a pattern of diseases characterized by extensive crescent formation in the glomeruli; patients present clinically with rapid deterioration of renal function, and possible progression to end-stage renal failure within weeks or months. "In crescentic glomerulonephritis pathogenesis, LAT2 was shown to be upregulated activating the mTORC1 pathway." (PMID 34124158, 2021). "Thus, LAT2-specific inhibitors might also be interesting and considered therapeutically for crescentic glomerulonephritis and other emerging LAT2-related diseases." (PMID 34124158, 2021).
diabetic retinopathy (1 paper, 2025). "Third, while five plasma proteins showed statistically significant causal associations with diabetic retinopathy in the forward MR analysis, only LAT2 passed all robustness checks, including Cochran’s Q test for heterogeneity." (PMID 40747309, 2025). "In conclusion, our integrative MR study identifies LAT2 as a novel and specific protective plasma protein against diabetic retinopathy, likely acting through immune-mediated pathways involving memory B cells." (PMID 40747309, 2025). "LAT2 may be a potential protective factor for diabetic retinopathy, offering preliminary insight for future biomarker development and prevention strategies." (PMID 40747309, 2025). "Together, these findings suggest that the protective effect of LAT2 against DR may be partly mediated by CD27+ switched memory B cells, highlighting the importance of adaptive immune pathways in the pathophysiology of diabetic retinopathy." (PMID 40747309, 2025).
glioblastoma (1 paper, 2021). The most malignant astrocytic tumor (WHO grade IV). "Third, the brain uptake of 3-l-[18F]FPhe in healthy rats, which is likely to be primarily mediated by LAT1 and LAT2, showed almost the same time course as the tumor uptake of this tracer in the glioblastoma model." (PMID 34885141, 2021).
Glucose intolerance (1 paper, 2025). Glucose intolerance (GI) can be defined as dysglycemia that comprises both prediabetes and diabetes. "SLC7A8 (LAT2) facilitates amino acid transport and its deficiency prevents diet-induced obesity, reduces glucose intolerance, limits lipid accumulation in multiple organs, and diminishes macrophage infiltration." (PMID 41458991, 2025).
hearing loss (1 paper, 2025). "LAT2 mutations have been described as contributing to the early onset of both hearing loss and cataract growth in human populations." (PMID 40546137, 2025).
helminth infection (1 paper, 2023). "Thus, in the context of mucosal helminth infection, ILC2-intrinsic expression of the amino acid transporters LAT1 and/or LAT2 is required for optimal effector immune responses." (PMID 36571761, 2023).
Hyperammonemia (1 paper, 2022). An increased concentration of ammonia in the blood. "This review focuses on the effects of hyperammonemia on the two glutamine carriers located in the astrocytic membrane: Slc38a3 (SN1, SNAT3) and Slc7a6 (y + LAT2)." (PMID 35733937, 2022).
Hyperbilirubinemia (1 paper, 2021). An increased amount of bilirubin in the blood. "Whether hyperbilirubinemia and BDL also alter the expression and functions of LAT2 protein still needs further investigation." (PMID 34680437, 2021).
hypothyroidism (1 paper, 2022). Abnormally low levels of thyroid hormone. "Another strain of Lat2 knockout mice only reported decreased T4 and slightly decreased T3 in serum at P21 without hypothyroidism in the liver and brain, whereas the Mct8/Lat2 double knockout had a significant increase of liver DIO1 expression at P0 compared to the Mct8 single knockout." (PMID 36499435, 2022).
inflammatory bowel disease (1 paper, 2025). A spectrum of small and large bowel inflammatory diseases of unknown etiology. "LAT2 was linked to Tuberculosis, Cell Adhesion Molecules, Hematopoietic Cell Lineage, Th1 and Th2 Cell Differentiation, Inflammatory Bowel Disease, AMPK Signaling Pathway, Carbon Metabolism, Ribosome, Cysteine and Methionine Metabolism, and Tyrosine Metabolism." (PMID 40607411, 2025).
Intellectual disability (1 paper, 2024). "Furthermore, we identified one patient with a smaller 167.21-kb microdeletion within the WSCR, including EIF4H, LAT2, RFC2, and CLIP2, but not comprising the ELN gene and segregating in the family with non-syndromic intellectual disability." (PMID 39368701, 2024).
intrauterine growth restriction (1 paper, 2018). "The human placenta displays a wide range of transporters for thyroid hormones from early gestation: MCT8, MCT10, LAT1, LAT2, OATP1A2 and OATP4A1; the observed expression patterns are different between pregnancies with normal physiology and pregnancies affected with intrauterine growth restriction." (PMID 29375646, 2018).
kidney damage (1 paper, 2024). "For instance, glutamine, one of the amino acids transported by the LAT2/4F2hc complex, has been reported to significantly decrease kidney damage and improve kidney function by modulating oxidative stress and apoptosis in murine tubular epithelial cells." (PMID 38890684, 2024).
laryngeal carcinoma (1 paper, 2021). Carcinoma that arises from the laryngeal epithelium. "Our data confirmed that RCN1, DNAJA2, LASP1 and IBSP were up-regulated while LAT2, FUZ, HOOK2 and DAPK2 were down-regulated in laryngeal cancer." (PMID 34976784, 2021). "Moreover, LAT2 (HR: 0.525901, 95% CI: 0.320208-0.863728, p-value = 0.011127) and HOOK2 (HR: 0.458976, 95% CI: 0.25448-0.827801, p-value = 0.009654) were protective factors for laryngeal cancer." (PMID 34976784, 2021).
myeloma (1 paper, 2013). "Furthermore, myeloma cells predominantly express the large amino acid transporter 1 (LAT1) and tyrosine preferentially enters cells via LAT2." (PMID 24376850, 2013).